IL4 (interleukin 4)
Diseases named in the same sentence as IL4 in open-access papers (continued):
Sharing a sentence is not in itself a finding about the gene and the disease.
Allergy (continued). "Th2 cells can secrete IL-3, IL-4, IL-5, IL-10, and IL-13, and these cells can thereby mediate B-cell differentiation through IL-4, participate in allergic reactions and mediate macrophage deactivation through IL-4, IL-10 and IL-13." (PMID 36225183, 2022). "Interleukin-4 (IL-4) is a major cytokine secreted by T-helper type 2 (Th2) and supports immunoglobulin class switching to IgE, and thereby development of allergy." (PMID 34038479, 2021). "In this allergy type, the allergens promote the proliferation of T helper 2 (Th2) cell, resulting in IL-4 release, followed by the antigen-specific IgE production." (PMID 34836277, 2021). "During Cul exposure when allergic horses had clinical allergy, IL-4 secretion from PBMC after stimulation with Cul extract was similar between healthy and CH affected horses." (PMID 34038479, 2021). "Cd1d1 codes for CD1d, a lipid-binding molecule on the surface of IECs and DCs that presents lipid antigens to invariant natural killer T 2 (iNKT2) cells, leading to the release of IL-4, which promotes the differentiation of Th2 cells and allergy expansion." (PMID 34684302, 2021). "Pro-inflammatory cytokines (e.g., IL-12, IL-25 and IL-13) play an important role in driving allergic conditions including allergic asthma; IL-33, IL-4 and IL-5 are key factors that drive allergy." (PMID 34638811, 2021). "Allergen-specific IgE represents only a subfraction of the receptor bound IgE on basophils and crosslinking with anti-IgE resulted in similar secretion of IL-4 from cells of both groups independent on their allergy status." (PMID 34038479, 2021). "We found that IL-4 is significantly negatively associated with ASD severity via CARS total score, which likely indicates that allergy as an ASD co-morbidity is more common in those with mild-to-moderate ASD rather than severe ASD." (PMID 33642989, 2021). "In the context of clinical allergy, repeated exposure to certain allergens promote a “modified allergy” milieu in which Th2-derived IL-4 and Treg-derived IL-10 combine to induce IgG4 production." (PMID 34305927, 2021). "Accordingly, manipulating the actions of IL-4 has broad ramifications, including related to allergy, cancer, and even the central nervous system." (PMID 34557875, 2021). "An increase in regulatory cytokine IL-2 and TGF-β was detected, as was the reduction of IL-4, IL-17, and IL-1β, reflecting the cancer patient's immunosuppressive environment and the lower prevalence of allergies." (PMID 34518597, 2021). "Despite its prominent role in allergy and immunity to parasitic infection, IL-4 also has known importance in inducing B cell response and humoral immunity." (PMID 34215212, 2021). "In contrast, Th2 cytokines produce the cytokines IL-4, IL-10, and IL-13, which stimulate the production of antibodies directed toward large extracellular parasites, including allergies." (PMID 34945585, 2021). "The type 2 Th (Th2) dominance is a key feature of atopy or allergy as these cells predominantly produce interleukin 4 (IL-4), IL-5, and IL-13, which are involved in the initiation and perpetuation of the allergic phenotype." (PMID 33668787, 2021). "As a primary activator of Th2 cells, IL-6 leads to the secretion of IL-4 and IL-13, promoting the Th2 immune response, which is considered pivotal in the pathogenesis of allergy." (PMID 33525403, 2021). "Allergy is an inflammatory process determined by a cascade of immune events characterized by T-helper 2 lymphocytes polarization leading to interleukin-4 upregulation, IgE secretion, and mast cell and eosinophil activation." (PMID 35082780, 2021). "On the level of allergy, Th2 suppression reduces IL-4 cytokine levels, decreased IgE production and suppressed mast cell activity." (PMID 34444774, 2021). "On the other hand, Type 2 T-helper (Th2) cells mainly secrete interleukins (ILs) including IL-4, IL-5, and promote B cells to secrete immunoglobulin E (IgE) antibodies to promote humoral immunity and induce allergy response." (PMID 33535602, 2021).
Allergy (continued). "Major histocompatability complex type II MHC II-binders, interleukin-4 and -10 inducers, interferon γ -inducers and immunobioactivity tools were used to predict the peptide-power of inducing allergies or tolerance." (PMID 33466712, 2021). "These function as alarm signals activating ILC2s to produce the Th2 cytokines IL-4, IL-13 and IL-9, with critical roles in type 2 immunity and allergy." (PMID 33803079, 2021). "IFN‐γ inhibits the collection of eosinophils by inhibiting CD4+ T cell infiltration, reducing IL‐4 and IL‐5 production, inhibiting the synthesis of IgE, and attenuating allergy‐induced airway inflammation." (PMID 33421348, 2021). "Alternatively, the Th2 cytokine IL-4 elicits M2 macrophage production, inducing helminthic immunity, allergy, and other immunomodulatory activities 3-7." (PMID 33754034, 2021). "Our finding that basophils produce early IL-4, shortly after allergen stimulation, is also consistent with work in murine allergy models, which show basophils as the primary source of the initial IL-4 during allergic responses." (PMID 34038479, 2021). "The results of the present study reveal novel and essential roles of Gαi1/3 proteins in the control of IL-4 signaling, macrophage functions and M2 polarization, with broad implications for regulation of Th2 immunity, inflammation, and allergy." (PMID 33754034, 2021). "IL‐4 is an indispensable molecule in allergic reactions, inducing homotypic conversion to IgE, up‐regulating adhesion molecules and promoting eosinophil migration." (PMID 34092045, 2021). "In allergic reactions periostin is involved in type 2 immunity and can be induced by IL-4 and IL-13 in bronchial cells." (PMID 34512647, 2021). "In contrast, type 2 interleukin (IL)-4/IL-5/IL-13-secreting Th (Th2) cells defend against helminth infections and venom exposure and participate in different types of allergic diseases, including asthma, atopic dermatitis, allergic rhinitis, and food allergy." (PMID 34945585, 2021). "ILC2s synthesize and secrete Th2 cytokines (IL-4, IL-5, IL-9, and IL-13), which promote eosinophils and mast cells to participate in allergic reactions." (PMID 34659628, 2021). "IL4 is a cytokine that plays a crucial role in the progression or pathogenesis of allergic diseases since it has a key role in the development of helper T-cell and the production of IgE." (PMID 34394070, 2021). "ILC2s respond quickly to allergic reactions mainly by secreting type 2 cytokines and other peptides, such as IL-4, IL-5, IL-13, IL-9, and amphiregulin (Areg), and by intercellular regulation of the cell-to-cell pathway." (PMID 34177881, 2021). "AD is recognized as a T helper 2 (Th2)–mediated allergic disease, accompanied by increases in cytokines such as tumor necrosis factor α (TNFα), interleukin 4 (IL-4), and IL-17." (PMID 33708782, 2021). "Largely related Th2 cells can secrete IL-4 and other cytokines, which play an important role in fighting parasitic infections and allergic diseases." (PMID 35006213, 2021). "TNF-α and IL-4 play critical roles in activating immune cells to produce other cytokines and IgE antibodies that aggravate allergic reactions." (PMID 34576749, 2021). "IL-4 and IL-13 are central to type-2 inflammation; therefore, they represent targetable candidates for the amelioration of allergic disease." (PMID 34072723, 2021). "These cells produce cytokines characteristic of the Th1-dependent response (IL-2, IFN-γ) and Th2 cells (IL-4, IL-5, IL-10) so they can play both protective and pathogenetic roles in allergic diseases, depending on the disease phase." (PMID 33435598, 2021). "In the recall phase, T cell infiltration conversely promotes the activity of ILC2s via the release of IL-2 and IL-4 and via B cells to promote the development of allergic reactions." (PMID 34177881, 2021). "IL-4 is related with allergic reaction, therefore, Adhatoda can be useful in the treatment and control of allergic diseases such as allergic rhinitis." (PMID 33884360, 2021).
Allergy (continued). "Cells were either activated with LPS/IFN-γ, as classical type-1 inflammatory stimulus, or IL-4, to simulate a type-2 cytokine-driven inflammation, which is characteristic in allergic reactions." (PMID 34769126, 2021). "Following the early phase of allergic reactions, cytokines release including IL-4, IL-5, IL-6, and TNF-α, enhances IgE synthesis." (PMID 33927634, 2021). "Human and mouse studies additionally suggest that basophils have a unique role in the regulation of allergic diseases by providing initial IL-4 to drive T cell development towards the Th2 phenotype." (PMID 34038479, 2021). "In the early phase of IgE-mediated allergic reaction, some types of cytokines such as IL-4 and IL-13 will be released by activated T lymphocytes and will interact with B lymphocytes to induce the synthesis of allergen-specific IgE." (PMID 33927634, 2021). "Allergy is characterized by the activation of CD4+ Th2 cells and the production of Th2 associated cytokines, such as IL4, IL5, and IL13, as well as levels of IgE, which activates mast cells." (PMID 33255731, 2020). "Oral administration of L. reuterii, a gram-positive bacterium similar to FP, in a mouse allergy model has been reported to decrease Il4 and Ifng, and increase Il10 mRNA expression in the spleen." (PMID 32184789, 2020). "This treatment regulated many immune reactivities, with decreased inflammatory cytokines in inflammatory colitis, decreased skin graft rejection in a transplant model, and decreased IgE and IL-4 sensitization in a rodent allergy model (to ovalbumin (OVA))." (PMID 32377529, 2020). "Th2-related cytokine (IL-4/IL-5) was increased by the allergy induction and aggravated by E2 treatment, while administration of API inhibited its level." (PMID 32765268, 2020). "IL-4 is one of the important cytokines required for anti-inflammatory responses against inflammatory conditions such as MS and allergies." (PMID 32102262, 2020). "The secretion of mediators by these immune cells, such as the allergy-related Type 2 cytokines IL-4 and IL-13, but also reactive oxygen species and proteases, contribute to the damage of the epithelium." (PMID 33374733, 2020). "IL4 induces B-cell class switching to IgE and upregulates MHC class II production, which is associated with allergies." (PMID 33379227, 2020). "IL-4 and IL-13 play an important role in mediating allergic reactions which can promote the induction of IgE syntheses and the development of mast cells." (PMID 33256200, 2020). "Th2 cells are thought to play a key role in the onset of allergic reactions, given that this class of cells produces the pro-inflammatory cytokines interleukin (IL)-4, IL-5, and IL-13, and induces the differentiation of B cells into plasma cells." (PMID 32184789, 2020). "IL-4 activation of FoxP3+ Tregs influences their ability to maintain barrier immunity through their regulatory function of ILC2 activation during allergic disease." (PMID 32931477, 2020). "We have shown that extended exposures increase Th2 immune responses, and that chemical co-exposures can increase markers of allergic disease including IL-4 levels and total IgE." (PMID 33373420, 2020). "Bovine PBMCs and synthetic peptides together seem to serve as a good model for pursuing the BTV-induced IL-4 activity that precedes the development of an allergic reaction, although further optimization of the protocol is warranted." (PMID 33375108, 2020). "Th2 cells are the main T cell subsets involved in allergic diseases, which release effector cytokines, such as IL-4, IL-10, and IL-13, that will interact with B cells for the synthesis of allergen-specific IgE." (PMID 33224143, 2020). "In contrast, Th2 cells mainly secrete IL-4, IL-3, IL-6, and IL-10 to stimulate the proliferation of activated B cells, to produce antibodies, and to participate in humoral immune-related or allergic diseases." (PMID 33659270, 2020).
Allergy (continued). "Dual targeting of IL-4 and IL-13 with Dupilumab, a monoclonal antibody targeting IL-4Rα, has recently entered the clinic for certain allergic diseases." (PMID 32754154, 2020). "Cytokine traps targeting IL-33, TSLP, IL-4 and IL-13 are novel tools that nicely complement the use of monoclonal antibodies for the treatment of allergic diseases." (PMID 32754154, 2020). "For instance, IL-4, an important cytokine in allergic reactions, induces VCAM-1 in microvascular endothelial cells." (PMID 33321726, 2020). "Th2 cells can also be regulated by the transcription factor GATA-3 and secrete IL-4, IL-5, IL-13 and other effector cytokines to regulate allergic reaction." (PMID 33194780, 2020). "In this allergy type, the specific invading antigens (allergens) promote proliferation of the Th2 cell, which releases IL-4, resulting in antigen-specific IgE production." (PMID 31426284, 2019). "Th2 are closely involved in allergy; their immune response involves the production of IL-4, IL-5, and IL-13, which lead to the recruitment and activation of mast cells, basophils and eosinophils, and goblet cell hyperplasia in airway mucosa." (PMID 31683763, 2019). "It is established knowledge in the allergy field that Th2-derived IL-9 and IL-4/IL-5 induce goblet cell hyperplasia either directly or indirectly via neutrophilic granulocytes, respectively." (PMID 30845208, 2019). "IL-4 strongly stimulates B lymphocytes and leads to switching to IgE, which is important in the pathomechanism of allergy, and was also observed in the presented experiment." (PMID 31487844, 2019). "Immunotherapy of allergic disease reduces the formation of IL-4 specific Th2 lymphocytes and increases the production of IFN-gamma specific Th1 lymphocytes." (PMID 30857564, 2019). "TSLP is widely known to induce Th2 responses by elevating Th2 cytokines such as IL-4, IL-5, and IL-13 in allergic diseases, including AD." (PMID 31817146, 2019). "Meanwhile, the late phase of an allergic reaction occurring hours after sensitisation will trigger the release of cytokines such as IL-4, IL-5, IL-9, IL-13, TNF-α and IFN-γ that will recruit inflammatory cells and further bring about mast cell degranulation." (PMID 31829185, 2019). "Th2 interleukins such as IL-4 and interleukin 5 (IL-5), leads to immunoglobulin E (IgE) production and inducing of the growth of mucosal-type mast cells which can resulted in allergic response." (PMID 31156785, 2019). "This DCS device is potentially capable of detecting interaction levels between IL-4 and IL-13, and subsequently triggering the release of designed ankyrin repeat protein (DARPin) E2_79 when an allergic reaction is recognised." (PMID 31226821, 2019). "Whereas, late phase of the allergic reaction is recognized by the release of cytokines such as IL-13, IL-4, IL-9, IL-5, IFN-γ and TNF-α after 2 to 6 h of sensitisation." (PMID 31829185, 2019). "Similar results have been reported by our group in a BLG-sensitized mice model, in which we found that the administration of LGG added to EHCF elicited a significant reduction of allergic reaction, and of IL-4, IL-5, IL-13 and specific IgE production." (PMID 30828329, 2019). "IL-4 and IL-13 are essential for the allergic reactions, which can promote the production of IgE in the plasma B cells." (PMID 30800677, 2019). "IL-4 and IL-4Rα are involved in allergic disease, and KD patients have been reported to exhibit an atopic trend." (PMID 31269967, 2019). "ILC2s are key drivers of allergic disease and upon activation express very high levels of IL-5, IL-6, and IL-13, but also secrete many other cytokines, including IL-4, GM-CSF, IL-9, and IL-10." (PMID 31024538, 2019). "The roles for IL-4, IL-5, IL-13, and GM-CSF in allergic diseases are well established, and it is clear that iBET151 has the potential to suppress these responses in ILC2." (PMID 31024538, 2019).
Allergy (continued). "IL-4 and IL-13 as well as the IL-4 receptor complexes that they bind to play key roles in the pathogenesis of allergic diseases." (PMID 31861989, 2019). "Some cytokines such as TNF-α and IL-4 can be used as fascinating therapeutic target molecules for IgE-mediated allergic responses and proinflammatory Th2 cell responses in allergic diseases." (PMID 31871471, 2019). "Fenugreek extract prevented the differentiation of Th2 cells in splenocytes of mice with allergy, reducing the secretion of IL-4 and expression of GATA-3 mRNA, an IL-4 transcription factor." (PMID 30513929, 2018). "The analysis of serum cytokines showed that piglets with FOS supplementation had higher interferon-γ level, but lower levels of IL-4 and IL-10 compared with the allergy group." (PMID 30524396, 2018). "In mouse and human allergies, IL-4 initiates TH2 responses and IgE isotype class switching, whereas IL-5 and IL-13 are important for eosinophil infiltration/activation and increased airway hyperreactivity in allergic asthma." (PMID 29696026, 2018). "More recently, mitochondrial Ca2+/calmodulin-dependent protein kinase II has emerged as key mediator of the molecular response in allergy, regulating eotaxin, IL-4, IL-5, IL-13, and eosinophilic inflammation." (PMID 29890625, 2018). "These complex modes of IL-4 and IL-13 action have great implications in the design of effective allergy therapies." (PMID 29868002, 2018). "Microbes in the allergy group were correlated positively to specific IgG, IL-4, and IL-10 and were correlated negatively to IFN-γ." (PMID 30524396, 2018). "Th 1 cells and Th2 cells are acted as immune response pattern, it also has been reported that Th2 cells produce IL-4 which stimulate lymphocyte B cells to produce IgE for increasing allergy immune response in scabies infected patient." (PMID 30483339, 2018). "In a randomized double-blind placebo-controlled trial individuals with allergic rhinitis Spirulina significantly reduced the levels of IL-4 that is important in regulating immunoglobulin (Ig)E-mediated allergy." (PMID 29495393, 2018). "More recently, HDAC3 has been shown to be necessary to activate IL-4 and loss of HDAC’s limits IL-4 mediated allergic disease." (PMID 30562364, 2018). "During the pathogenesis of allergic disease, IL-4 is also crucial for the induction of IgE synthesis and mast cell development." (PMID 30618741, 2018). "Interleukin 4 (IL-4) is a critical cytokine implicated with TH2 immune reactions, which are linked to pathologic conditions of allergic diseases." (PMID 29915306, 2018). "Substantial progress has been made over the past 28 years in understanding the contribution of 4PS (IRS1 or IRS2) to IL-4- and IL-13-stimulated responses in the context of allergic diseases, however, as noted throughout, there is still much work to be done." (PMID 29868002, 2018). "The production of IL-4 by draining lymph node cells illustrates the cellular immune aspects of the allergic reaction." (PMID 30258210, 2018). "It has also been reported that QCT inhibits the antigen-immunoglobulin E mediated tumor necrosis factors-α and IL-4 production in Type I allergic reactions and concomitantly decreases the expression of Th2-type cytokines (IL-4, IL-13, and IL-5) by basophils." (PMID 30026677, 2018). "IL-4, originally termed B cell stimulatory factor-1, is a cytokine primarily known for its role in antibody driven-allergic disease and protection from parasite infections." (PMID 29755466, 2018). "Th9 cells are known to mediate inflammation, infection and allergy, and this lineage is differentiated in the presence of Th2-polarizing cytokine IL-4, in combination with IL-2 and TGFβ." (PMID 29371571, 2017). "The various allergy parameters IL-4 and IL-13, DARPin E2_79, the total IgE contained in the serum of the donors and the IgE-DARPin E2_79 complexes were monitored by ELISA (I-IV)." (PMID 29062109, 2017).